INS (insulin)
Diseases named in the same sentence as INS in open-access papers (continued):
Sharing a sentence is not in itself a finding about the gene and the disease.
Hyperglycemia (continued). "Here, we report the effects of imatinib on incident hyperglycaemia, circulating levels of glucoregulatory proteins, longitudinal insulin sensitivity and ACE-2 enzymatic activity in 385 hospitalized COVID-19 patients who participated in a randomized, double-blind, placebo-controlled clinical trial." (PMID 38424569, 2024). "Impaired insulin metabolic signaling, hyperglycemia-induced abnormal AGE/RAGE signaling, mitochondrial dysfunction, increased fatty acid utilization, and impaired calcium handling ER stress along with coronary endothelial dysfunction are considered pathogenic causes in T2DM-induced DCM." (PMID 38716357, 2024). "Insulin corrects hyperglycemia and ketone production, and it inhibits glucagon and lipolysis." (PMID 39360087, 2024). "In affected patients, extremely high levels of insulin, fasting hyperglycemia and failed responses to endogenous and exogenous insulin may be detected." (PMID 38397072, 2024). "This leads to hyperglycaemia and requires lifelong insulin therapy." (PMID 39408940, 2024). "The recommended course of treatment for hyperglycemia in GDM is the administration of insulin." (PMID 38396408, 2024). "Specifically, Miles demonstrated that AT mice maintain normal insulin sensitivity but experience transient hyperglycemia during an oral glucose tolerance test; Wu found that heterozygous mutation of the ataxia-telangiectasia mutated gene exacerbates hypercholesterolemia in apoE-deficient mice." (PMID 39326070, 2024). "This early hyperglycemia is usually transient but may still need insulin therapy to manage the situation until normoglycemia returns." (PMID 38674437, 2024). "According to Somogyi's hypothesis, insulin-induced hypoglycemia at night would stimulate the secretion of counterregulatory hormones or would induce eating, resulting in hyperglycemia the following morning." (PMID 39718705, 2024). "Studies have shown that polysaccharides and oligosaccharides from seaweed could reduce hyperglycemia, promote insulin secretion, improve glucose tolerance, lower blood glucose and urine glucose, and alleviate other symptoms in diabetic mice induced by alloxan." (PMID 39596859, 2024). "However, when these measures are insufficient to achieve and maintain adequate glycemic control, insulin is the drug of choice to treat hyperglycemia during pregnancy." (PMID 38559691, 2024). "Hyperglycemia is believed to stimulate the expression of MyoVa, contributing to insulin secretion." (PMID 38371125, 2024). "Furthermore, insulin inhibits hepatic glucose production by suppressing the expression of gluconeogenic genes, such as Pepck and G6pase, thereby preventing hyperglycemia." (PMID 39337550, 2024). "Following pancreatectomy, regardless of underlying diagnosis, all children should be evaluated to determine whether they are euglycemic, have persistent hypoglycemia, or have hyperglycemia requiring insulin treatment." (PMID 37454648, 2024). "Late-afternoon hyperglycemia may in part be the result of a tendency to better insulin action and lower hepatic insulin extraction at breakfast time than later in the day." (PMID 38982528, 2024). "The significant reduction in systemic circulation of insulin results in hyperglycemia which can lead to the accumulation of advanced glycation end products within bodily tissues and the development of complications such as nephropathy, neuropathy, retinopathy, and cardiovascular disease (CVD)." (PMID 38435452, 2024). "SITG’s ability to lower blood glucose levels and improve insulin sensitivity is crucial in mitigating the neurodegenerative effects of hyperglycemia, which might accelerate oxidative stress, inflammation, and the formation of AGEs." (PMID 39766390, 2024). "Both hyperglycemia and hyperinsulinemia could be involved in the detrimental effects of glucose consumption on muscle insulin sensitivity." (PMID 38201980, 2024).
Hyperglycemia (continued). "Our findings indicate that CLE may reduce low-grade inflammation and thus improve insulin sensitivity and postprandial hyperglycemia." (PMID 38347961, 2024). "Moreover, the presence of preoperative persistent hyperglycemia in geriatric patients suggests decompensated pancreatic function, indicating inadequate insulin secretion or insulin resistance within the body." (PMID 38977983, 2024). "Although maternal insulin does not cross the placenta, maternal hyperglycemia and other nutrient alterations can stimulate the fetal pancreas to increase insulin production and an increased risk of adiposity in the offspring of mothers with GDM." (PMID 37491556, 2024). "However, intraperitoneal injection with STZ selectively kills insulin-producing cells in the pancreas and leads to rapid hyperglycaemia with blood glucose levels reaching 20–25 mmol l−1 within 7 days (red highlighted area)." (PMID 37996616, 2024). "Although historically this has been attributed to reactive hyperglycemia and dysregulated insulin secretion, the pathophysiology is poorly understood, and faulty renal gluconeogenesis may contribute, at least in part, to this abnormality." (PMID 38743489, 2024). "The results presented here may have implications for trauma and critically ill patients suffering from trauma-induced metabolic dysfunction with hyperglycemia and increased insulin resistance." (PMID 38653969, 2024). "Notably, fed insulin levels were not increased in HFSD-fed vehicle-treated mice compared to LFD-fed mice, presumably because of HFSD-induced β-cell failure to compensate for insulin resistance, resulting in hyperglycemia." (PMID 39195275, 2024). "Insulin remains the primary treatment for managing hyperglycemia in this patient population." (PMID 38559691, 2024). "Additionally, a higher phenolic content has been associated with stronger enzymatic inhibition, and procyanidins isolated from grape seeds can lower hyperglycemia more effectively than low-dose insulin, exhibiting an insulin-mimetic effect." (PMID 39598440, 2024). "The attempt failed (severe hyperglycaemia after 36 h) and insulin therapy was restarted." (PMID 39457190, 2024). "Additionally, the occurrence of hyperglycemia, elevated the levels of insulin and leptin also contribute to the induction of oxidative stress." (PMID 38603728, 2024). "T2DM characterized with hyperglycemia due to impaired insulin secretion and/or action may lead to the down-regulation of IMD, indicating that IMD is involved in DCM." (PMID 39338366, 2024). "Finally, insulin preparation: Insulin is the most effective hypoglycemic drug and is a life-saving necessity for people with severe hyperglycemia." (PMID 39568669, 2024). "Thus, chronic hyperglycaemia impairs hepatic and cortical renal insulin signalling at the early steps, i.e., IR recruitment and activation are inhibited, as shown in the current study." (PMID 39339687, 2024). "Five RCTs investigated intermediate-acting insulin with the hypothesis that the insulin profile matches better with the insulin requirements in GC-induced hyperglycemia." (PMID 38281042, 2024). "Insulin is secreted by the pancreas during hyperglycemia in a biphasic manner." (PMID 39768947, 2024). "We reasoned that the effect of pramlintide cotreatment to lower serum glucagon:insulin ratio could be used alongside lower doses of liraglutide to enhance protection from olanzapine-induced hyperglycemia and enable lower doses of drugs to be used." (PMID 38188526, 2024). "More specifically, the review revealed that, while all dietary patterns induced a significant reduction in Hb1Ac levels after 12 weeks, the traditional Mediterranean diet emerged as the most efficacious in improving postprandial hyperglycaemia and insulin sensitivity at an equivalent body weight." (PMID 39229589, 2024).
Hyperglycemia (continued). "Several animal studies have suggested that baicalin improves metabolic function in skeletal muscle, adipose tissue, and liver by reducing lipid accumulation and enhancing insulin sensitivity, thus effectively suppressing hyperglycemia and improving insulin action." (PMID 39130628, 2024). "Despite nearly a century of insulin therapy for the management of hyperglycemia in T1D, no therapies exist to treat its underlying etiopathology." (PMID 39040994, 2024). "Chronic hyperglycemia stimulates the continuous release of insulin from pancreatic β cells." (PMID 38255314, 2024). "Resveratrol can also improve both β-cell insulin secretion and hyperglycemia." (PMID 38892574, 2024). "In addition to insulin secretion, hyperglycemia potentiated the increases in intracellular calcium signals by ucOC compared to cells maintained at lower glucose levels." (PMID 39125265, 2024). "Furthermore, we find that succinate functions as an incretin-like metabolite, which significantly potentiates insulin secretion in hyperglycemia in humans." (PMID 38713514, 2024). "According to this hypothesis, liver glucagon receptor activation stimulates insulin secretion by increased hepatic glucose production and hyperglycemia, and liver glucagon action may inhibit insulin secretion by stimulating KP production." (PMID 38599822, 2024). "By manipulating TGFβ signaling pathways, researchers may be able to enhance the efficacy of stem cell therapies and promote the differentiation of stem cells into β-cells to improve insulin production and manage hyperglycemia." (PMID 39604763, 2024). "However, two of these trials had a significant decrease in time during which glucose level was > 180 mg/dL in the HCL group, showing that the cases of hyperglycemia are potentially due to specific insulin pump management issues." (PMID 38602747, 2024). "Her main goal was to overcome her fear of insulin and resolve the toxic hyperglycemia." (PMID 39539363, 2024). "Moreover, insulin-producing cells derived from bone marrow stem cells have shown the ability to engraft and reverse hyperglycemia in mice." (PMID 39014283, 2024). "In the early postprandial phase, the release of Insulin from the beta cells of pancreas results in the formation of Insulin–IAA complexes which hinders the normal physiological action of insulin on glucose that leads to hyperglycaemia." (PMID 38428138, 2024). "In addition, RDR treatment in the STZ-induced diabetic rats remarkably improved the low body weight, polydipsia, polyphagia, hyperglycemia, and islet architecture and increased the insulin/glucose ratio." (PMID 39201631, 2024). "Centella blocks ATP-sensitive K+ channels to enhance insulin secretion and control hyperglycemia." (PMID 39519546, 2024). "In complementary studies, depletion of MFN1/2 found similar hyperglycemia, reductions in insulin secretion, and mitochondrial network fusion and respiration, however, these effects correlate more with effects on mitochondrial DNA (mtDNA) content rather than changes in fission/fusion." (PMID 38404962, 2024). "However, the patient was eventually converted to basal-bolus insulin therapy because of uncontrolled hyperglycemia." (PMID 39329041, 2024). "The increased presence of ROS in overweight and obese individuals may affect the apoptosis of Langerhans cells in the pancreas, disrupting the glucose-insulin balance and leading to hyperglycemia, further increasing OS levels." (PMID 38655176, 2024). "We hypothesized that osteoglycin levels increase during hyperglycemia as a physiological response to enhance the effects of insulin." (PMID 38549032, 2024). "On the other hand, progression to hyperglycemia and T2DM may be caused by impaired insulin secretion due to beta cell dysfunction or insulin insensitivity of target tissues." (PMID 38715798, 2024). "In patients with T2DM, BMI may regulate insulin secretion and thus affect glycemic excursions and/or postprandial hyperglycemia." (PMID 38468235, 2024).
Hyperglycemia (continued). "Decreased INSR expression may lead to an increase in insulin production as a compensatory response to hyperglycemia." (PMID 39337631, 2024). "A reduction in insulin dose requirement with GLP-1RA could raise the risk of DKA, which could partially explain the increased hyperglycemia with ketosis events in controlled settings." (PMID 39518671, 2024). "On the other hand, when the pathogenic GCK variant is not inherited, insulin secretion increases in response to maternal hyperglycemia, increasing the risk for macrosomia; in such cases, insulin treatment of maternal hyperglycemia is recommended." (PMID 39408828, 2024). "Low LDL-C may reflect abnormal cholesterol biosynthesis resulting from inflammation and oxidative stress secondary to chronic hyperglycemia and reduced insulin secretion." (PMID 39768591, 2024). "Thus, in T2D patients, β cells are exposed to two counteracting stimuli, glucagon‐induced hepatic glucose production, and hyperglycemia stimulation, whereas KP production inhibits glucose‐stimulated insulin secretion." (PMID 38599822, 2024). "Furthermore, environmental and genetic factors are involved with the initiation of chronic inflammation, insulin rersistance (IR), and the development of hyperglycemia in T2D5." (PMID 39676616, 2024). "Isoflurane anesthesia may impair glucose clearance and produce hyperglycemia likely through processes evoked by ATP-sensitive potassium channels in pancreatic β-cells leading to a decrease in insulin release and glucose utilization." (PMID 38794716, 2024). "In cases where, despite the efforts, hyperglycaemia is observed, insulin treatment needs to be introduced to maintain target glycaemic levels, which in turn may reduce the impact of hyperglycaemia on the subsequent adiposity in the offspring." (PMID 38308265, 2024). "This was an observational cohort study targeting mothers with gestational diabetes, which evaluated the association of maternal hyperglycemia severity, classified as GDM-G1 (diet treatment) and GDM-G2 (insulin treatment), with colostral adipokines involved in pro- and anti-inflammatory processes." (PMID 39795898, 2024). "Furthermore, the oversupply of FFAs to the liver exacerbates insulin resistance and promotes gluconeogenesis, aggravating hyperglycemia." (PMID 38999988, 2024). "Moreover, all T1DM volunteers took a dose of insulin adjusted to the expected exhaustive exercise, which protected them from hyperglycemia and led to stimulation by its metabolic changes." (PMID 39407919, 2024). "To test the hypothesis, we administered insulin to EV71-infected mice to correct hyperglycemia and determine its effect on animal survival." (PMID 38773966, 2024). "However, PI3K is an important mediator of the action of insulin, and the use of PI3K inhibitors has been associated with hyperglycemia." (PMID 39437820, 2024). "Hence, this study aims to explore and compare the anti-apoptotic and regenerative capabilities of MSCs-EXs loaded with either Se or NSe particles to alleviate hyperglycemia and restore normal insulin secretion from the pancreas of T1DM rats." (PMID 38666865, 2024). "Additionally, the use of a home or hospital pump reduced hypoglycemia and hyperglycemia in children when compared with children receiving insulin via subcutaneous injection." (PMID 38324312, 2024). "In contrast, reducing long-acting basal and prandial insulin concentrations before EXE decreases the risk of hypoglycemia during and after the activity, but may lead to hyperglycemia at other times of the day." (PMID 38542818, 2024). "For the first time, it was highlighted: (a) the role of TIR in the activation of the pAkt/CREB/BDNF pathway and the downstream signaling cascade; (b) TIR efficacy in neuroprotection; (c) TIR counteracting of hyperglycemia and insulin resistance-related effects at the neuronal level." (PMID 38287296, 2024).
Hyperglycemia (continued). "However, insulin therapy regimens are complex, with basal insulin used to control glucose overnight and between meals, bolus doses to control glucose at mealtime, and correction doses if needed for hyperglycemia." (PMID 39518671, 2024). "In addition, the destruction of insulin-mediated beta cell inhibition of alpha cells contributes to alpha cell hypertrophy and the eventual development of hyperglucagonemia and hyperglycemia." (PMID 39594662, 2024). "In the present study, the diabetic mice showed this important clinical feature of exercise intolerance that was completely alleviated by exercise training even under the condition of continued severe hyperglycemia, suggesting an insulin sensitivity-independent mechanism of exercise benefits." (PMID 38203804, 2024). "Based on Ca2+’s role in insulin release, we can conclude that nifedipine may be effective in diabetic patients, as hyperglycemia increases the intracellular level of Ca2+." (PMID 39204160, 2024). "Consequently, proband experienced reduced insulin synthesis and impaired beta cell function, leading to early‐onset hyperglycemia (MODY6)." (PMID 39264012, 2024). "Therefore, the aim of this study was to determine the ability of insulin to increase leg glucose uptake following exercise during hyperglycaemia resulting from ingestion of meals." (PMID 38662135, 2024). "Hyperglycemia-induced oxidative stress may affect the insulin signaling cascade, disturb the cellular redistribution of insulin signaling elements, decrease GLUT4 gene transcription, and alter mitochondrial activity." (PMID 39202758, 2024). "Consistent with the previous study, GK rats displayed impaired insulin secretion and hyperglycemia." (PMID 39300600, 2024). "In addition, flies fed a lipid-rich diet presented a systemic activation of JAK/STAT signaling, reduced insulin sensitivity, hyperglycemia, and a shorter lifespan, features that were all dependent on a macrophage-Unpaired 3 axis." (PMID 38716198, 2024). "Notably, in prediabetic conditions, there is evidence supporting an elevated insulin-induced OXPHOS status in response to persistent hyperglycemia." (PMID 38255314, 2024). "Additionally, the DEC group also had significantly higher rates of insulin response to hyperglycemia, i.e., administration of short-acting insulin when BG ≥ 200 mg/dL (66.4% vs. 46.3%, p < 0.001) with a comparable insulin sliding scale between groups." (PMID 39451871, 2024). "In brief summary and with minor variations, augmented responses of glucagon (AUC only in hypoglycemic clamp), cortisol, and ACTH and attenuated responses of GH in both clamps correlated with unfavorable metabolic phenotypes, such as adiposity, chronic hyperglycemia, and insulin resistance." (PMID 37708362, 2024). "This eight-week regimen increased body weight, blood glucose, and insulin levels to study the relationship between hyperglycaemia, which may also contribute to atherogenesis in db/db mice and the efficacy of PV in treating this dysfunction." (PMID 38675115, 2024). "IL-1β promotes inflammation and impairs insulin signaling, worsening hyperglycemia." (PMID 39840100, 2024). "In a Spanish cohort, MODY-X patients, in comparison with MODY2 or MODY3, presented higher levels of hyperglycemia and reduced insulin sensitivity, whereas, in a French study population, MODY-X individuals displayed a less aggressive clinical course than their counterparts affected by MODY3." (PMID 39201476, 2024). "Secondary outcomes included rates of maintaining euglycemia from POD1 until POD10 or hospital discharge, hospital length of stay (LOS), ICU LOS, mean glucose levels, rates of hyperglycemia (blood glucose > 180 mg/dL) and hypoglycemia (blood glucose < 70 mg/dL), and rate of restarting IV insulin." (PMID 39590191, 2024).